FSCN1 (fascin actin-bundling protein 1)
Diseases named in the same sentence as FSCN1 in open-access papers (continued):
Sharing a sentence is not in itself a finding about the gene and the disease.
tumor (continued). "Over-expression of FSCN1 or FOXM1 was associated with the tumour microenvironment and immune signatures in ACCs." (PMID 31783819, 2019). "For the first time, the potential association between tumour microenvironment and FSCN1 and FOXM1 was identified." (PMID 31783819, 2019). "Of all predicted mRNAs, we selected FSCN1, which has been previously implicated in tumor migration and invasion." (PMID 26010149, 2015). "When we analyzed the clinical aspects of rs852479 and rs1640233 FSCN1 and rs920778 HOTAIR genotypic frequencies among BC patients, we found that CC genotype of FSCN1 rs1640233 was significantly associated with developed tumor size and lymph node invasion (p-value = 0.04 and 0.02; respectively)." (PMID 38587571, 2024). "Furthermore, some studies have found that FSCN1 is aberrantly expressed in various cancers and is closely associated with the malignant behaviour of tumours." (PMID 36960218, 2023). "FSCN1 overexpression in intravascular tumor cells indicated increased metastatic risk, suggesting that FSCN1 may be an independent prognostic indicator for the different steps of extracellular matrix invasion 77-79." (PMID 35711849, 2022). "In addition, due to heterogeneity in different cancer cells and the complexity of multiple molecular mechanisms underlying tumor progression, evidence regarding FSCN1 roles in cancer development and progression is fragmented and limited." (PMID 33614909, 2021). "FSCN1, a fascin family member, was recently shown to be associated with tumor invasiveness in ACC and GNAI3 (guanine nucleotide binding protein (G protein), alpha inhibiting activity polypeptide 3) was shown to be increased in nutrient starved adrenal glands in RGS4ko mice." (PMID 34572898, 2021). "We also compared one-year treatment outcomes in HNSCC patients based on FSCN1 expression in tumor tissues and its concentration in blood serum." (PMID 40669873, 2025). "Among cytoskeletal effectors involved in tumour aggressiveness, FSCN1 has emerged as an attractive therapeutic target due to its differential expression in normal versus tumoural adrenocortical tissues." (PMID 41226387, 2025). "The authors note that in vivo studies are needed to assess the effects of FSCN1 inhibition on various cells in the tumor microenvironment." (PMID 40669873, 2025). "This was also confirmed by qRT‐PCR with significant upregulation of fibronectin (FN1), fascin (FSCN1), and the receptor tyrosine kinase AXL, which has been associated with EMT, tumor cell invasion, and therapy resistance in different tumor entities." (PMID 40066744, 2025). "The relative number of FSCN1+ tumor cells in tissue samples was shown to correlate with HNSCC progression." (PMID 40669873, 2025). "In H295R cells, inhibition or silencing of FSCN1 disrupted filopodia formation and reduced proliferation, and in zebrafish xenograft models, FSCN1 knockdown impaired both tumour growth and metastatic spread." (PMID 41226387, 2025). "In the current study, we demonstrated the role of FSCN1 in the progression of HNSCC by analyzing serum levels of FSCN1 and estimating the number of cells expressing FSCN1 in the tumor and the number of CTCs containing this protein." (PMID 40669873, 2025). "It was also found that the relative number of FSCN1+ CTCs in the bloodstream is greater than that of FSCN1+ tumor cells in the primary tumor tissue." (PMID 40669873, 2025). "DCs located in DC_3 with the high expression of Ccr7 and Fscn1 displayed a mregDC (mature DC enriched in regulatory molecules) signature, which was crucial for inducing tumor‐directed T‐cell responses." (PMID 39574346, 2025). "Fascin homologous 1 (FSCN1) was identified as a direct target of miR-539, a tumor suppressor, and its high expression level enhanced the aggressiveness of HCC cells." (PMID 38568089, 2024).
tumor (continued). "As an oncogene, FSCN1 can influence mitochondrial remodeling in cancerous cells, in addition to promoting invasion, tumor migration, metastatic colonization, cancer cell self-renewal, and drug resistance." (PMID 38587571, 2024). "The positivity rate of FSCN1 protein in tumor stage II–IV group (23.3%, 7/30) was higher than in stage I patients (10.2%, 8/78), but the difference was also not statistically significant (P = 0.147)." (PMID 38698008, 2024). "FSCN-1 also affects the tumor microenvironment by influencing the behavior of stromal cells and the extracellular matrix." (PMID 39682247, 2024). "FSCN1 has been observed to be a direct target of several tumor suppressor miRNAs, such as miR-143-3p and miR-145-5p." (PMID 38542153, 2024). "Downregulation of miR-145-5p oncogenes like FSCN1 (fascin actin-bundling protein 1) at the protein level or SOX2 causes migration, invasion, tumour growth, and EMT." (PMID 39518152, 2024). "Findings suggested a strong correlation between the expression of FSCN1 and some clinicopathological characteristics, such as high histological grade, tumor necrosis, and status of ER- and PR-negativity." (PMID 38587571, 2024). "In numerous malignant tumors, FSCN1 exhibits upregulation, suggesting its potential as an oncogenic factor, as it fosters tumor cell migration and invasion." (PMID 38370379, 2024). "By qRT‐PCR analysis of characteristic lung metastasis signature genes, namely ID1 and FSCN1, using the original and tumor derived cell lines, we found that derived cells had higher expression than their parental cell lines." (PMID 37518985, 2023). "In PCa, FSCN1 expression has been reported in PCa stromal cells in tumours with high Gleason scores and in tumour cells in a CRPC sample." (PMID 37875732, 2023). "Here, we investigated the association of FSCN1 with pre-invasive (PanIN) and invasive (PDAC) lesions in a small cohort of human samples from resected PDAC tumours with associated PanIN lesions." (PMID 37832352, 2023). "The results presented here support previous work from our group using in vitro and murine models which found that SNAI2 expression was seen in low grade PanIN and induced FSCN1 expression in cells cultured from tumours." (PMID 37832352, 2023). "Because FSCN1 has been described as an important protein for invadopodia formation, which are crucial for tumour cell invasion in cancer progression, we evaluated the ability of LNCaP cells to form invadopodia under androgen-deprivation conditions." (PMID 37875732, 2023). "In accordance with the results of cellular experiments, we verified the role of the PTOV1-AS2/miR-145-5p/FSCN1 axis in an in vivo nude mouse tumor model." (PMID 36960218, 2023). "Our results also showed that the treatment of METRO-TOPO (6-weeks EE) downregulates FSCN1 expression in subclonal populations in aggressive mCRPC/NEPC 3D tumor models, whereas CONV-TOPO resulted in increased expression (P < 0.05)." (PMID 37476073, 2023). "Mechanistic studies revealed that ZEB1-AS1 functions as a “sponge” for miR-200b to regulate the expression of FSCN1, a globular actin-bundling protein that is important in cancer cell migration and invasion during tumor progression." (PMID 36605618, 2023). "The hyperexpanded and large TCR types mainly existed in C1qb+ and especially Fscn1+ macrophages, which mainly existed in tumor tissues." (PMID 36718369, 2023). "Characterization of FSCN1 knockout mice has shown that FSCN1 is dispensable for brain development, but indispensable for developmental retina angiogenesis and tumor angiogenesis." (PMID 37596693, 2023). "NP-G2-044 was initially identified as a FSCN1 inhibitor and has demonstrated anti-tumor potency in a phase Ia clinical trial (Clinicaltrials.gov NCT03199586)." (PMID 37596693, 2023). "In tumor cells, de novo expression of Fscn1 correlates with their invasive and metastatic properties." (PMID 35681718, 2022).
tumor (continued). "Here, we downloaded and reanalyzed the expression of FSCN1 in all tumor and normal cervical tissues of TCGA, which also showed high expression of FSCN1 in tumor cervical tissues." (PMID 35178306, 2022). "In vitro experiments with ECA-109 and KYSE-150 and ex vivo experiments in tumor-bearing mice were performed to investigate the effects of FSCN1 and Protein Tyrosine Kinase 6 (PTK6) on ESCC progression." (PMID 35401239, 2022). "Similar to tumor cells, DCs require Fscn1 to exert migratory activity but also for their interaction with T cells in order to mount antigen-specific T-cell responses." (PMID 35681718, 2022). "Understanding the molecular mechanism by which FSCN1 functions in tumor metastasis will aid in identifying a more suitable therapeutic target for metastatic cancer." (PMID 35178306, 2022). "To date, several Fscn1 inhibitors that block interaction of Fscn1 with F-actin in order to inhibit tumor metastasis have been developed and successfully evaluated in vitro and in preclinical models." (PMID 35681718, 2022). "TUNEL and EdU were also detected in the tumor tissues, which showed that apoptosis was inhibited by FSCN1-OE but promoted by PTK6-T2, and proliferation was facilitated by FSNC1-OE but restrained by PTK6-T2." (PMID 35401239, 2022). "In response to the expression of Fscn1, tumor cells were reported to display increased migratory activity, thereby enhancing the invasive and metastatic properties of the tumor." (PMID 35681718, 2022). "Fascin actin-bundling protein 1 (FSCN1), an actin-bundling protein associated with cell migration and invasion, is highly expressed in various tumor tissues." (PMID 35178306, 2022). "In vivo animal experiments also confirmed that miR-585-3p targets FSCN1 to inhibit tumor growth and block the MAPK signaling pathway." (PMID 35602576, 2022). "FSCN1 is highly expressed in various tumor tissues, is involved in the formation of filopodia in tumor cells, and plays an important role in the initial stage of tumor cell migration and invasion." (PMID 35178306, 2022). "The actin-bundling protein Fscn1 has attracted attention as a target protein in cancer therapy due to its requirement for tumor metastasis." (PMID 35681718, 2022). "The tumor volume and weight of the FSCN1-OE group were significantly larger than those of the control group, whereas they were substantially smaller in the PTK6-T2 group, suggesting that FSCN1 promotes EC growth by inhibiting PTK6." (PMID 35401239, 2022). "Pharmacological Fscn1 inhibitors, which are currently under clinical trials for tumor therapy, were demonstrated to counteract tumor metastasis." (PMID 35681718, 2022). "In tumor cells, de novo expression of Fscn-1 correlates with their invasive and metastatic activities." (PMID 35681718, 2022). "Accordingly, a number of pharmacological Fscn1 inhibitors have been developed, which impaired tumor cell migration in vitro by inhibiting the interaction of Fscn1 with F-actin and accordingly attenuated tumor growth in preclinical mouse models." (PMID 35681718, 2022). "The significant functions of FSCN1 in tumor cell migration, invasion, and metastasis depend on its role in actin cytoskeletal reorganization and on the activities of FSCN1-mediated cell signaling pathways." (PMID 33614909, 2021). "To explore the function of FSCN1 in tumor biology, we first analyzed the characteristics of FSCN1 gene expression." (PMID 34249689, 2021). "With respect to imbalanced tumor growth, contrasting results have been reported upon in vitro manipulations of FSCN1 expression levels in cell lines." (PMID 33614909, 2021). "In summary, this study reveals a novel mechanism by which LYAR promotes tumor cell migration and invasion by upregulating FSCN1 expression and affecting fatty acid metabolism in CRC." (PMID 35069968, 2021). "Increasing evidence showed that FSCN1 is involved in cell proliferation, apoptosis, motility, chemotherapeutic resistance, tumor growth, and metastasis of several malignancies." (PMID 34733789, 2021).
tumor (continued). "A novel pathway for function of the transcription factor LYAR in CRC has also been revealed: LYAR promotes tumor migration and invasion by upregulating FSCN1 expression, which in turn positively regulates fatty acid metabolism." (PMID 35069968, 2021). "They revealed that the small molecule compound G2 inhibits the actin-bundling function of FSCN1 and blocks tumor cell migration, invasion, and metastasis." (PMID 33614909, 2021). "In our study, the expression of POSTN, TNC, CAV1 and FSCN1 found to be localized predominantly in the cytoplasm of the tumour cells." (PMID 33739025, 2021). "documented that coordinated regulation of intracellular FSCN1 distribution is important for tumor microvesicle release." (PMID 33614909, 2021). "Although novel actin-independent roles of FSCN1 have been discovered, they do promote tumor cell migration and invasion through the formation of filopodia and invadopodia." (PMID 33614909, 2021). "The expression of POSTN, TNC, CAV1 and FSCN1 was localized predominantly in the cytoplasm of the tumour cells." (PMID 33739025, 2021). "Regarding PCa, apart from already published data that demonstrated overexpression in tumor tissue using immunohistochemistry, our results on FSCN1 as a new biomarker in PCa patients must be seen with limited potential." (PMID 34737886, 2021). "Several studies of multiple cancer types have also shown that the downregulation of FSCN1 through siRNA or shRNA is effective at suppressing tumor cell metastasis in vivo." (PMID 33614909, 2021). ",3,5, 6, 7, 8, 9 Functional studies have revealed that FSCN1 promotes tumor cell migration, invasion, and metastasis." (PMID 33614909, 2021). "Upregulated FSCN1 in human tumors is functionally involved in tumor cell migration, invasion, and metastasis." (PMID 33614909, 2021). "Other studies have shown that migrastatin and its analogues target FSCN1 and block its activity, thereby reducing cell migration, invasion, and tumor metastasis." (PMID 34830909, 2021). "In most of the tumor cell lines, FSCN1 knockdown by siRNA inhibited cell migration and invasion in vitro." (PMID 33614909, 2021). "Studies have reported that manipulation of FSCN1 expression in cancer cells affects tumor cell growth and proliferation." (PMID 33614909, 2021). "In summary, FSCN1 is a multifunctional protein that plays an important role in regulating various cellular physiological processes in normal and tumor cells." (PMID 33614909, 2021). "Targeted inhibition of FSCN1 functions with small molecule inhibitors blocking tumor cell migration, invasion, and metastasis." (PMID 33614909, 2021). ",9,11,12,281In vitro manipulation of FSCN1 expression in tumor cell lines has shown that FSCN1 promotes tumor cell growth, migration, invasion, and metastasis." (PMID 33614909, 2021). "Immunohistochemical studies have demonstrated that FSCN1 overexpression in the tumor correlates with a decreased OS and with different aspects of carcinoma invasiveness." (PMID 34248854, 2021). "Selective block of FSCN1 in the tumor has been recently described to inhibit the metastatic process and stimulate anti-tumor immune responses in several mouse models of solid tumors." (PMID 34248854, 2021). "The role of FSCN1 in tumor cell migration and invasion has been correlated to its actin-bundling activity." (PMID 33614909, 2021). "Our study also reveals that FSCN1 expression is correlated with the expression of YWHAZ, which encodes the 14-3-3ζ protein, and that silencing FSCN1 downregulates YWHAZ only in tumor cells with PIK3CA alterations." (PMID 34249689, 2021). "The expression of FSCN1 can be enhanced by transforming growth factor-beta (TGF-β) treatment in spindle-shaped tumor cells in a Smad-dependent manner." (PMID 33614909, 2021). "Bestatin was found to significantly inhibit tumor cell migration and invasion by blocking FSCN1 promoter and reducing its expression, thus acting as a plausible anti-metastatic therapeutic agent." (PMID 34830909, 2021).
tumor (continued). "In breast and kidney cancer, the frequency of FSCN1-positive tumors tended to increase with tumor invasion and metastasis." (PMID 33614909, 2021). "Several studies have also documented that targeted inhibition of FSCN1/actin bundling blocks tumor cell migration and metastasis." (PMID 33614909, 2021). ",33,278, 279, 280 It is foreseeable that creative agents (siRNAs, small molecule inhibitors, nanobody, etc.)will be developed to specifically inhibit FSCN1-mediated tumor metastasis." (PMID 33614909, 2021). "A statistically significant positive correlation was found between serum concentration of FSCN1 and FSCN1 levels in tumor tissues of the 10 ACC patients analyzed by ELISA technique." (PMID 34248854, 2021). "FSCN1 expression is also higher in hepatocellular carcinoma tissues compared with normal liver tissues which significantly correlates with the tumor grade, lymph node invasion, and distant metastasis in addition to poor prognosis." (PMID 34830909, 2021). ",77,80,82,101,104,109,117,156, 157, 158, 159 miR-133a/b directly targets FSCN1 in a variety of human cancers and acts as a tumor suppressor." (PMID 33614909, 2021). "Through siRNA knockdown, we confirmed that the pro-tumor effect of LINC01711 was mediated through modulating FSCN1 expression." (PMID 34370713, 2021). "The tumor tissues showed that FSCN1 protein expression levels were increased upon LINC00152 overexpression, whereas miR‐185‐3p and miR‐632 agomirs treatment can reverse this effect." (PMID 32042551, 2020). "Four proteins (FSCN1, SIPA1, SPTBN1 or CD59) closely associated with tumor metastasis interacted with FASN and exhibited decreased expression in response to FASN silencing." (PMID 32699531, 2020). "And the current results provided another method to suppress the expression of FSCN1 through the tumor-suppressive function of miR-488 by directly binding to the 3′UTR region of FSCN1." (PMID 33099573, 2020). "On the 32nd day, we observed that the tumor proliferation of nude mice injected with FSCN1-knockdown cells was slower than the control cells both in CAL-27 and SCC-25 cell lines." (PMID 31043585, 2019). "To clarify the relationship between FSCN1 expression and its influence on tumorigenic capacity in nude mice, we injected FSCN1-knockdown and control cells into mice and marked the tumor volume over time." (PMID 31043585, 2019). "When the tumors were cut into slices and stained by immunohistochemistry, we found that the tumor cells were less dense and exhibited lower proliferation in the control cells than in the FSCN1-knockdown cells." (PMID 31043585, 2019). "Knockdown of FSCN1 correlated with lower progression and less trans-migration in vitro and decreased tumor growth in vivo." (PMID 31043585, 2019). "Inhibition of FSCN1 reduces cancer migration and tumor metastasis in prostate and oral squamous cancer cells." (PMID 29162880, 2017). "Recent studies have found that miR-145 functions as a tumor suppressor and that miR-145 overexpression suppresses migration and invasion in prostate cancer and bladder cancer by targeting FSCN1." (PMID 26010149, 2015). "Several studies have reported that FSCN1 is overexpressed in malignant tumors, and is generally correlated with its aggressive behavior by increasing cell motility and tumor invasiveness." (PMID 26503504, 2015). "From several candidates, we selected FSCN1 for further experiments because FSCN1 has been found to play important roles in tumor migration and invasion." (PMID 26010149, 2015). "The actin-bundling protein Fascin (FSCN1) is a tumor marker that is highly expressed in numerous types of cancer including lymphomas and is important for migration and metastasis of tumor cells." (PMID 25105941, 2014). "Re-introduction of miR-133b into GC cells can obviously inhibit GC cell proliferation, migration and invasion and the tumor suppressor roles of miR-133b in GC was partially through targeting oncogenic FSCN1." (PMID 25433493, 2014).